SIRT3 (sirtuin 3)
Diseases named in the same sentence as SIRT3 in open-access papers (continued):
Sharing a sentence is not in itself a finding about the gene and the disease.
cardiac hypertrophy (continued). "Studies have demonstrated that miR-214 directly targets and suppresses sirtuin 3 (SIRT3), leading to mitochondrial dysfunction and thereby promoting the development of angiotensin II (Ang-II)-induced cardiac hypertrophy." (PMID 41602333, 2026). "In our previous study, we found that increased SIRT3 expression in the myocardium of a porcine model of pathological myocardial hypertrophy effectively inhibited the expression of MMP2 and MMP9, limiting the progression of pathological myocardial hypertrophy." (PMID 40893347, 2025). "miR-214 can suppress SIRT3, leading to mitochondrial dysfunction, cardiac hypertrophy and eventual failure." (PMID 40501482, 2025). "UTMD-mediated targeted delivery of Sirt3 can repress cardiac hypertrophy, and preserve cardiac function." (PMID 40959490, 2025). "SIRT3 can also reduce the accumulation of hypertrophy-associated lipids in the heart through deacetylation of LCAD, thereby slowing the development of cardiac hypertrophy." (PMID 40710369, 2025). "2-APQC is a SIRT3 activator that regulates mitochondrial homeostasis, alleviating myocardial hypertrophy and fibrosis." (PMID 41567643, 2025). "Overexpression of miR-214 exacerbated mitochondrial damage and facilitated cardiac hypertrophy, whereas genetic knockdown of miR-214 restored SIRT3 expression and attenuated mitochondrial dysfunction." (PMID 40501482, 2025). "Berberine improves cardiac insufficiency and cardiac hypertrophy in DCM mice by regulating SIRT3‐mediated lipid metabolism, promoting lipophagy, and reducing high glucose‐induced cellular lipotoxicity." (PMID 41276460, 2025). "For example, small molecules, such as 2-APQC and C12, that enhance SIRT3 activity, have shown promise in protecting against cardiac hypertrophy, neurodegeneration, and metabolic disorders in animal models." (PMID 40799515, 2025). "SIRT3 knockout mice exhibit age-dependent mitochondrial dysfunction due to prolonged pore opening, displaying cardiac hypertrophy, fibrosis, and increased sensitivity to cardiac stress." (PMID 40799515, 2025). "Surprisingly, SIRT4 promotes Ang II‐induced cardiac hypertrophy and remodeling via enhanced oxidative stress and inhibits SIRT3‐mediated manganese superoxide dismutase deacetylation." (PMID 41180381, 2025). "The deletion of SIRT3 specifically in cardiomyocytes also leads to age‐dependent hyperacetylation and cardiac hypertrophy in 10‐month‐old mice." (PMID 41180381, 2025). "Studies have shown that SIRT3 has cardioprotective effects and can effectively reduce myocardial hypertrophy, fibrosis, and injury." (PMID 41276460, 2025). "SIRT3 is thought to protect the heart from oxidative stress and mitochondrial damage, inhibit ferroptosis, and ameliorate cardiac hypertrophy and fibrosis in DCM." (PMID 41276460, 2025). "In cardiac hypertrophy models, SIRT3 has been shown to regulate the transcription factor FOXO3A through deacetylation, promoting its translocation from the mitochondria to the nucleus." (PMID 40799515, 2025). "SIRT3 participates in severalheart diseases, such as heart failure, cardiac hypertrophy, atherosclerosis,and dilated hypertrophy." (PMID 38261767, 2024). "After SIRT3 knockout, myocardial hypertrophy worsened and the area of fibrosis increased in the ISO group." (PMID 38744811, 2024). "Inhibition of p300 using a specific inhibitor C646 reversed cardiac fibrosis, hypertrophy, and cardiac function by improving coronary flow reserve in Sirtuin 3 (SIRT3) knockout mice." (PMID 38427976, 2024). "CD38 also serves as a crucial factor in cardiac hypertrophy by inhibiting SIRT3 expression and activating the Ca2+-NFAT signaling pathway." (PMID 38347953, 2024). "Similar findings have been discovered in our study, a low expression in SuHx-induced rat model and CoCl2-induced H9c2 cell hypoxia model.On the contrary, the expression of SIRT3 can reduce the apoptosis of cardiomyocytes in a cardiac hypertrophy model." (PMID 38750550, 2024).
cardiac hypertrophy (continued). "ACh prevents cell apoptosis by inhibiting the action of angiotensin II (Ang II) and inhibits ROS production as well as cardiac hypertrophy by the activation of sirtuin 3/AMP-activated protein kinase (SIRT3-AMPK) signaling." (PMID 39280620, 2024). "SIRT3 has been previously demonstrated to counteract cardiac hypertrophy in primary cultures of cardiomyocytes by activating MnSOD and catalase, thereby decreasing cellular levels of ROS." (PMID 37558995, 2023). "Conversely, SIRT3 overexpression or activation via pharmacological agents can alleviate or even prevent cardiac hypertrophy under pressure overload or treatment with hypertrophic agonists." (PMID 37237500, 2023). "SIRT3 has also been studied in the heart and shown to protect against both cardiac hypertrophy and I/R injury, while SIRT6 KO mice exhibit cardiac hypertrophy." (PMID 37728319, 2023). "SIRT3 expression is increased during the early stages of cardiac hypertrophy induced by transverse aortic constriction (TAC), isoproterenol, or Ang II infusion." (PMID 37237500, 2023). "SIRT3 delays the progression of heart failure and cardiac hypertrophy by improving mitochondrial biogenesis and by reducing reactive oxygen species (ROS) cellular levels." (PMID 36675125, 2023). "While Sirt3-expressing transgenic (Tg) mice are protected from cardiac hypertrophy, endothelial-specific Sirt3KO (ECKO) mice show myocardial capillary rarefaction along with reduced coronary flow reserve (CFR) and diastolic dysfunction." (PMID 36675125, 2023). "Omentin1 reduces myocardial hypertrophy by upregulating the SIRT3/FOXO3a signaling pathway, thereby initiating mitochondrial autophagy to maintain mitochondrial dynamic balance." (PMID 37754811, 2023). "SIRT3 performs a role in the development of various cardiovascular diseases, ranging from cardiac hypertrophy to dilated cardiomyopathy and heart failure." (PMID 37237500, 2023). "The activation of Sirt3, by increased levels of NAD+ induced by CD38 deficiency, activates AMPK, which suppresses Ang-II-induced cardiac hypertrophy by inhibiting the AKT-glycogen synthase kinase3β (GSK3β)-NFATc pathway." (PMID 36831262, 2023). "For instance, there is evidence that SIRT3 is a negative regulator of cardiac hypertrophy via the activation of FOXO3a-dependent anti-oxidants and by impeding mtROS-mediated Ras activation and downstream MAPK/ERK and PI3K/Akt signaling." (PMID 37371077, 2023). "The activation of SIRT3 promotes autophagy and alleviates Ang II-induced cardiac cell hypertrophy, whereas the silencing of SIRT3 exacerbates myocardial hypertrophy." (PMID 37754811, 2023). "Our results show that the cardiomyocyte-specific deletion of SIRT3 is pathological, with decreased cardiac function, cardiac hypertrophy, and evidence of fibrosis." (PMID 36460774, 2023). "Honokiol inhibits the hypertrophic response and pressure overload cardiac hypertrophy by activating SIRT3." (PMID 35571098, 2022). "SIRT3 is involved in the pathogenesis of diverse disorders including cancer, diabetes, neurodegeneration, cardiac hypertrophy, and liver steatosis." (PMID 35571098, 2022). "Hyperoside blocks the AKT pathway, which reduces the protein expression of B-type natriuretic peptide and β-myosin heavy chain by angiotensin II (Ang II) or enhances SIRT3 signal expression to improve cardiac hypertrophy." (PMID 35566359, 2022). "Honokiol (HK) has previously been reported to improve myocardial ischemia/reperfusion injury and reverse myocardial hypertrophy by activating Sirt1 and Sirt3." (PMID 35264952, 2022). "Sesamin, a well-known antioxidant derived from sesame seeds, has been shown to improve cardiac function and prevent ventricular hypertrophy by activating the SIRT3/ROS pathway." (PMID 35571098, 2022). "The hearts of whole body SIRT3-KO mice exhibit cardiac hypertrophy, interstitial fibrosis, contractile dysfunction and inflammation." (PMID 35369299, 2022).
cardiac hypertrophy (continued). "SIRT3 reduces intracardiac hypertrophy-related lipid accumulation and alleviates the progression of cardiac hypertrophy by deacetylation of LCAD." (PMID 35855865, 2022). "Studies using models of cardiac hypertrophy show that SIRT3 inhibits ROS production by various means." (PMID 35369299, 2022). "In contrast, some studies have revealed that Sirt3−/− mice have ATP levels that are less than half those of wild-type mice and that Sirt3−/− mice have a tendency to develop cardiac hypertrophy at a younger age than wild-type mice." (PMID 36100663, 2022). "It has been demonstrated that SIRT3 can deacetylate CypD, an important mitochondrial matrix protein, improving cognitive dysfunction, myocardial reperfusion injury, and cardiac hypertrophy." (PMID 36092157, 2022). "It has previously been observed that HK reduces oxidative stress and reverses cardiac hypertrophy by activating Sirt1 and Sirt3, respectively." (PMID 35264952, 2022). "Whole-body SIRT3-KO mice show signs of cardiac hypertrophy and interstitial fibrosis by 8 weeks and exhibit a 19% reduction in lifespan." (PMID 35369299, 2022). "SIRT3 represses aging-related and stress-induced cardiac hypertrophy and fibrosis by deacetylating FOXO3 and manganese-containing superoxide dismutase (MnSOD) to reduce the levels of mitochondrial ROS." (PMID 35855341, 2022). "Sirt3 inhibited cardiac hypertrophy by stimulating the Forkhead box O3a-dependent (Foxo3a-dependent), manganese superoxide dismutase (MnSOD) or superoxide dismutase 2 (SOD2) and catalase (Cat), thus suppressing cellular levels of ROS in primary cardiomyocytes." (PMID 35052850, 2022). "Emodin blocks agonist-induced and pressure overload-mediated myocardial hypertrophy and plays an important role in alleviating myocardial hypertrophy by regulating the mitochondrial Sirt3 signaling pathway." (PMID 36618923, 2022). "It has previously been observed that HK reduces oxidative stress and reverses cardiac hypertrophy by activating Sirt1, Sirt3, and Nrf2, respectively." (PMID 35264952, 2022). "A recent study in cardiac hypertrophy reported SIRT3-dependent enhancement of ketone body metabolism via AMPK-mediated increase in the levels of monocarboxylic transporters 1 (MCT1) and 3-oxoacid CoA-transferase (OXCT1)." (PMID 35369299, 2022). "It was shown to preserve mitochondrial function and structure, ameliorate cardiac hypertrophy, and improve overall cardiac function via activation of the SIRT3 in spontaneously hypertensive rats." (PMID 35369299, 2022). "In contrast, during diabetes, the initial stages of cardiac hypertrophy are marked with elevated SIRT3 expression." (PMID 35369299, 2022). "On the other hand, miR-214 aggravates cardiac hypertrophy by targeting and inhibiting sirtuin 3 (SIRT3), impairing mitochondrial function and perturbing energy metabolism." (PMID 35681500, 2022). "The hearts of SIRT3 knockout mice show accelerated signs of aging, manifested by cardiac hypertrophy and fibrosis." (PMID 35571098, 2022). "Overexpression of SIRT3 protects mice from phenylephrine-induced cardiac hypertrophy, while SIRT3 KO acts in the opposite direction." (PMID 34899370, 2021). "SIRT3 expression in the course of cardiac hypertrophy rises in moderate hypertrophy but falls in pronounced hypertrophy, so it behaves differently than the expression of SIRT1." (PMID 34899370, 2021). "Previous research has also found a role for SIRT3 in the context of cardiac hypertrophy, as transgenic mice overexpressing SIRT3 were reportedly protected from the development of angiotensin II‐induced cardiac hypertrophy." (PMID 34405591, 2021). "There are multiple interventional studies focused on the involvement of SIRT3 pathways in cardiac hypertrophy." (PMID 34829803, 2021). "A decreased deacetylation of fatty acid oxidizing enzymes leads to the accumulation of lipids in the mitochondria, but the overexpression of SIRT3 inhibits cardiac hypertrophy by decreasing lipid accumulation." (PMID 34829803, 2021).
cardiac hypertrophy (continued). "SIRT3 KO mice have cardiac inflammation, fibrosis, lower ATP levels and develop cardiac hypertrophy at an early age." (PMID 34829803, 2021). "To explore the effect of SIRT3 on Ang II‐induced cardiac hypertrophy, we conducted a series of experiments." (PMID 34180125, 2021). "SIRT3, a mitochondrial sirtuin protects the heart against myocardial hypertrophy, diabetic cardiomyopathy, and DIC." (PMID 33795647, 2021). "In one study, inhibition of PIKfyve resulted in the prevention of myocardial apoptosis and cardiac hypertrophy mediated through the activation of sirtuin-3 (SIRT3), a major mitochondria NAD+-dependent deacetylase in obese mice." (PMID 32540927, 2021). "In summary, the present study provides evidence that quercetin ameliorates cardiac hypertrophy by protecting mitochondrial structure and function in SHRs and Ang II-induced H9c2 cells, involving the SIRT3/PARP-1 pathway." (PMID 34776960, 2021). "In mice, the deletion of endothelial SIRT3 increases oxidative phosphorylation, reduces glycolysis and impairs angiogenesis, leading to diastolic dysfunction, cardiac hypertrophy and an age-related decrease in heart function." (PMID 34829803, 2021). "Since previous studies suggested a protective role of SIRT3 in cardiac hypertrophy, we assessed SIRT3 levels in rats by western blot." (PMID 34776960, 2021). "SIRT6 is located predominately in the nucleus and similarly to SIRT3 protects the heart from cardiac hypertrophy and DIC105." (PMID 33795647, 2021). "Treatment with honokiol, a potent SIRT3 activator, prevents and reverses ventricular hypertrophy and preserves mitochondrial integrity and energetic capability." (PMID 34239697, 2021). "The purpose of this study was to confirm that quercetin alleviated cardiac hypertrophy, focusing on the SIRT3/PARP-1 pathway both in spontaneously hypertensive rats (SHRs) and H9c2 cells." (PMID 34776960, 2021). "For example, our lab and others found that emodin inhibited class I and II HDAC activity and activated Sirt3 in both cell culture and animal models of cardiac hypertrophy." (PMID 33668293, 2021). "Recent studies have shown that sirtuin 3 (SIRT3)/poly (ADP-ribose) polymerase-1 (PARP-1) pathway modulation inhibits cardiac hypertrophy." (PMID 34776960, 2021). "This is supported by a previous study which found SIRT3 activation by NAD+ is necessary to blunt isoproterenol‐induced cardiac hypertrophy." (PMID 34405591, 2021). "In models of cardiac hypertrophy, SIRT3 mRNA, protein expression and enzymatic activity are constitutively reduced." (PMID 34829803, 2021). "Some of SNRK’s cardiac function are reminiscent of mitochondrial sirtuin proteins specifically SIRT3, wherein Sirt3 knockout mice are highly sensitive to stress, which leads to cardiac hypertrophy, fibrosis, and increased mortality." (PMID 32968716, 2020). "Our results indicate that SIRT3 exerts protective effects against cardiac hypertrophy by reducing the level of acetylation and activity of PARP-1, thus providing novel mechanistic insights into SIRT3-mediated cardiprotective actions." (PMID 32139662, 2020). "Recent evidence suggests Sirt-3 potentially has a role in limiting cardiac hypertrophy as it is found to be downregulated in mouse hypertrophic hearts." (PMID 32116760, 2020). "Many studies have reported that Sirt3 plays a crucial role in the pathogenesis of various cardiac diseases, such as cardiac hypertrophy, heart failure, and doxorubicin-induced cardiomyopathy." (PMID 33233476, 2020). "SIRT3 has been reported to have a protective effect against cardiac hypertrophy and interstitial fibrosis by augmenting antioxidant defense mechanisms." (PMID 31936371, 2020). "The decrease of SIRT3 and SIRT6 activity in the SIRT family can cause significant cardiac hypertrophy phenotype." (PMID 32139662, 2020).
cardiac hypertrophy (continued). "Transgenic mice with global SIRT3 overexpression improved endothelial dysfunction and attenuated vascular oxidative stress, while SIRT3 depletion promoted endothelial dysfunction and exacerbate vascular hypertrophy in hypertension." (PMID 32933152, 2020). "Many studies have focused on examining the cardioprotective role of Sirt3 in cardiac hypertrophy and heart failure." (PMID 33014281, 2020). "Cyclophilin D (CypD), which is an integral part of the mitochondrial permeability transition pore (mPTP), can be deacetylated by SIRT3 at lysine 166 to prevent the opening of mPTP, thus inhibiting stress-induced cardiac hypertrophy and apoptosis." (PMID 32724473, 2020). "For example, Sirt3 knockout mice exhibited severe cardiac hypertrophy and fibrosis induced by TAC, and nevertheless, cardiomyocyte-specific overexpression of Sirt3 resisted cardiac fibrosis and oxidative damage following angiotensin II infusion." (PMID 33014281, 2020). "It is worth noting that our previous study found DHY attenuated transverse aortic constriction induced myocardial hypertrophy through SIRT3 enhancement." (PMID 32933152, 2020). "By upregulating SIRT3, they have displayed promising therapeutic effects in some diseases such as cardiac hypertrophy, acute kidney injury, and others." (PMID 32724473, 2020). "SIRT3 can active the activity and nuclear translocation of FOXO3α, thereby inhibiting mTOR and Rho/Rho kinase signaling and preventing cardiac hypertrophy." (PMID 32724473, 2020). "Sirt3, a mitochondrial deacetylase enzyme, has a preventive effect against cardiac hypertrophy through regulating the mitochondrial function by the deacetylation of mitochondrial proteins, particularly SOD2." (PMID 33233476, 2020). "Recently, HKL, known as a pharmaceutical SIRT3 activator, has been found to block pressure overload-induced cardiac hypertrophy by increasing SIRT3 activity." (PMID 31936371, 2020). "The protective role of SIRT3 in cardiac hypertrophy has been reported by several studies, but its main role is concentrated in the cytoplasm, and nuclear SIRT3 based anti-hypertrophic mechanism remains to be elucidated." (PMID 32139662, 2020). "SIRT3 is involved in the development of many cardiovascular diseases, from cardiac hypertrophy to dilated cardiomyopathy, heart failure, and atherosclerosis." (PMID 32139662, 2020). "Studies have shown that many small molecules with Sirt3-activating property can protect against cardiac hypertrophy and heart failure." (PMID 33014281, 2020). "In the ISO-induced in vivo cardiac hypertrophy model, nucleoproteins of heart tissues were extracted, and SIRT3 and PARP-1 interactions were also detected by CO-IP." (PMID 32139662, 2020). "Recently, honokiol (HKL), as a pharmaceutical SIRT3 activator, has been observed to have a protective effect against pressure overload-induced cardiac hypertrophy by increasing SIRT3 activity." (PMID 31936371, 2020). "Surprisingly, the HFD induced cardiac hypertrophy only in female SIRT3 ECKO mice as evidenced by an increased HW/tibia length ratio." (PMID 33371209, 2020). "In the ISO-induced SD rat cardiac hypertrophy model, the results of immunohistochemistry showed that the total expression of SIRT3 protein and the distribution in the cytoplasm and nuclear were significantly increased." (PMID 32139662, 2020). "Since fibrosis and inflammation are crucial in the progression of cardiac hypertrophy, heart failure, and diabetic cardiomyopathy, our results point to SIRT3 as a potential target for treating these diseases." (PMID 32296036, 2020). "The induction of autophagy as well as the deacetylation of FOXO1 by SIRT3 reduces myocardial hypertrophy following treatment with angiotensin II." (PMID 31492861, 2019). "Sirtuin-3 also regulates mitochondria functioning and cardiac hypertrophy via the deacetylation of isocitrate dehydrogenase (IDH2)." (PMID 31434333, 2019).